MTOR (mechanistic target of rapamycin kinase)
Diseases named in the same sentence as MTOR in open-access papers (continued):
Sharing a sentence is not in itself a finding about the gene and the disease.
cervical carcinoma (continued). "In our study, we discovered that AMPK activation induces H3K9 hyperacetylation and inhibits cervical cancer growth in vivo and in vitro; this mechanism may be facilitated by an AMPK-dependent mechanism mediated by mTOR signaling inhibition." (PMID 38831454, 2024). "Therefore, TRIM21 promoted autophagy in cervical cancer by inhibiting NCAPH and the downstream AKT/mTOR pathway." (PMID 39103348, 2024). "Additionally, activation of PI3K/mTOR signaling pathway mediated by FNDC3B was found to induce invasion and metastasis in cervical cancer." (PMID 38581008, 2024). "Thus, our findings suggest that naringenin has therapeutic impacts on cervical cancer via multiple mechanisms, primarily by inhibiting the migration and invasion through the EGFR/PI3K/AKT/mTOR pathway." (PMID 38253629, 2024). "Our data demonstrated a novel molecular pathway in cervical cancer, that is, TRIM21 degrades NCAPH through K-11 ubiquitination, thus inhibiting the activation of the downstream AKT/mTOR pathway, promoting autophagosome formation and inhibiting cell proliferation." (PMID 39103348, 2024). "Of note, currently available studies assessing the therapeutic effects of mTOR inhibition included recurrent cervical cancer patients irrespective of potential mTOR-pathway alterations." (PMID 37623437, 2023). "The current study intended to explore how ERBB3 mediates the PI3K/AKT/mTOR pathway and changes the tumor immune microenvironment to affect the EMT status of cervical cancer, which may provide further understanding of MMPs involved in immunotherapy." (PMID 36911370, 2023). "In cervical cancer, the suppression of CD155 activates the apoptosis and autophagy of tumor cells, inhibiting the proliferation and tumor formation by inducing G0/G1 cell-cycle arrest, through inhibiting the AKT/mTOR/NF-kB signal pathway." (PMID 36358792, 2022). "Thus, ESM1 overexpression is important for PI3K-Akt- mTOR activation and EMT in cervical cancer cells." (PMID 36522312, 2022). "Accordingly, in cervical cancer cells, SHI diminished the expression of AKT and mTOR." (PMID 35267423, 2022). "Moreover, ADRA2A overexpression induces antiproliferation, apoptosis, and anti-migration/invasion in cervical cancer cells, accompanied by suppressing PI3K/AKT/mTOR." (PMID 36139919, 2022). "In pCCa-1 and pCCa-2 cervical cancer cells, SKI-V (10 μM, 3h) significantly suppressed phosphorylation of Akt (Ser-473) and S6K (Thr-389), indicating that SKI-V inhibited Akt-mTOR cascade activation in cervical cancer cells." (PMID 35541904, 2022). "Our results are also consistent with those of a previous study in which miR-155 transfection in human nasopharyngeal cancer and human cervical cancer cells inhibited several components of PI3K-Akt-mTOR signaling, including RHEB, RICTOR, phosphorylated mTOR and Akt." (PMID 36076283, 2022). "We speculate that E7 activates the AKT/mTOR pathway, and the latter promotes RCC1 S11 phosphorylation in cervical cancer cells." (PMID 34356619, 2021). "The utilization of mTOR inhibitors could reduce TRIM28-induced cell proliferation, suggesting that it could be used as a potential therapeutic target for cervical cancer." (PMID 33817325, 2021). "Furthermore, we demonstrated a new mechanism that the cisplatin-induced up-regulation of BCAT1 decreased the cisplatin sensitivity in cervical cancer and HCC cells by regulating mTOR-mediated autophagy via BCAA metabolism." (PMID 33568627, 2021). "To determine whether CD155 regulates the AKT/mTOR pathway in cervical cancer cells, we examined the expression of AKT, p-AKT, mTOR, p-mTOR, p-4EBP1, and p-P70S6K expression, which are critical molecules in the AKT/mTOR pathway." (PMID 34164340, 2021). "For the small number of HPV-negative cervical cancers, over-activation of the PI3K/AKT/mTOR pathway or mutations of its regulatory factors, such as PTEN, EGFR, and HER2, accounted for the virus-independent etiology of carcinogenesis." (PMID 34589516, 2021).
cervical carcinoma (continued). "Baicalein, a medicine agent screened from natural flavonoids targeting TGFβ pathway, could suppress mTOR/p70S6K pathway-mediated cell proliferation and EMT pathway-related migration via TGFβ pathway in cervical cancer HeLa cells." (PMID 33777154, 2021). "In summary, the present study found that baicalein is an inhibitor of TGFβ pathway, and it could suppress mTOR/p70S6K pathway-mediated cell proliferation and EMT pathway-related cell migration via TGFβ pathway in cervical cancer HeLa cells." (PMID 33777154, 2021). "S. flavescens inhibits cervical-cancer-cell proliferation and metastasis and induces apoptosis by inhibiting the AKT/mTOR signaling pathway; reducing the expression of Bcl-2, cyclin A and MMP2; blocking the G2/M phase cell cycle; and stimulating Bax and E-calmodulin." (PMID 34680171, 2021). "Although both AKT/mTOR and Wnt/β-catenin pathways have been investigated in cervical cancer respectively, no studies have been reported on the regulation of these pathways by GHET1 in CC." (PMID 31682716, 2020). "Li and his colleagues have reported that miR-99b could suppress cervical cancer cell proliferation, invasion, migration and cell cycle by the inhibition of the PI3K/AKT/mTOR signaling pathway." (PMID 31651329, 2019). "Hence, it is essential to develop additional agents with unique activity against both PI3K/AKT/mTOR and MAPK/ERK pathways in cervical carcinoma." (PMID 28490807, 2017). "Our results also suggested PKM2 enhanced sensitivity to cisplatin through interaction with the mTOR signaling pathway in cervical cancer, indicating that PKM2 may be a promising target for therapeutic approaches in cervical cancer, as well as other cancers." (PMID 27492148, 2016). "Updating of PGRN-stimulated mTOR signaling can better our understanding of the critical role of PGRN in physiologic and disease processes but also provides new therapeutic interventions for PGRN in malignancies, including cervical cancer." (PMID 27517315, 2016). "To evaluate whether this interaction involved in modulating cisplatin sensitivity in cervical cancer, we then investigated the effect of suppression of PKM2 on cisplatin sensitivity with additional mTOR inhibition." (PMID 27492148, 2016). "In this study, we investigated mammalian target of rapamycin (mTOR) signaling in response to PGRN induction and the contribution of the PGRN-stimulated PI3K/Akt/mTOR signaling pathway in the transformation and progression of cervical cancer." (PMID 27517315, 2016). "mTOR, HIF1α, c-Myc, and PKM2 expression in cervical cancer may serve as predictive biomarkers to cisplatin-based chemotherapy." (PMID 27492148, 2016). "A PGRN-stimulated mTOR signaling pathway was identified in non-transformed cervical mucosa epithelial cells and malignant cervical cancer cells." (PMID 27517315, 2016). "Whether mTOR, HIF-1α, and c-Myc are involved with PKM2 expression in cervical cancer patients receiving cisplatin-based NACT remains unclear." (PMID 27492148, 2016). "mTOR activation is frequently observed in cervical squamous cell carcinoma, most HPV(+) head and neck squamous cell carcinomas (HNSCC), HPV(+) oropharyngeal cancers (OPSCC), cervical cancer squamous cell carcinomas (CCSCC) lesions and cell lines." (PMID 26022660, 2015). "Taken together, the reduction of protein synthesis could reduce DVL3 expression in cervical cancer cell lines and that the decrement of DVL3 mediated by AMPK activators is mainly through the AMPK/mTOR signaling cascade." (PMID 23301094, 2013). "However, only limited published data are available on new mTOR inhibitors and the detailed mechanism of AZD8055 in treating cervical cancer has yet to be fully understood." (PMID 23420667, 2013). "In fact, treatment of an mTOR inhibitor, Rapamycin, could abolish DVL3 in cervical cancer cell lines." (PMID 23301094, 2013).
cervical carcinoma (continued). "In U2OS cells, TSA promoted autophagy by inhibiting the mTOR (mammalian target of rapamycin) signaling pathway and enhancing forkhead box O1 (FOXO1) transcriptional activity, while it induced autophagy through regulating the PRMT5/STC1/TRPV6/JNK pathway in cervical cancer cells." (PMID 40283998, 2025). "The role of FAM83A is ambiguous in cervical cancer, with one study showing a tumor‐suppressive role that involves regulation of integrins, whereas others reporting an oncogenic function mediated via PI3K/AKT/mTOR pathway, epithelial mesenchymal transition (EMT) and Wnt signaling pathway." (PMID 38914812, 2024). "Therefore, the anti-cervical cancer effect of SS may be mediated through the disruption of intracellular energy balance, which activates the AMPK/mTOR/FOXO3a pathway, thereby inhibiting cell proliferation and promoting apoptosis and autophagy." (PMID 39199249, 2024). "Given that PIK3CA is well known to be overexpressed in cervical cancer and that miR-29a has demonstrated growth inhibitory effects in various tumors by modulating the PI3K/AKT/mTOR signaling pathway, we conducted this study to determine whether miR-29a directly affects PIK3CA." (PMID 39590348, 2024). "Thus, further study is needed to investigate whether TNF-α could affect the progression of cervical cancer via targeting other pathways, such as AMPK/mTOR or the NF-κB signaling pathway." (PMID 37124061, 2023). "Therefore, we concluded that ADAMTS12 may affect the mTOR signaling pathway through the interacting with TGF-β1, and then affect the biological function of cervical cancer cells." (PMID 37642715, 2023). "As mTOR inhibition previously demonstrated therapeutic effects in cervical cancer, and cervical cancer expresses ER, investigating the rationale of the BOLERO−2 trial in cervical cancer could appear promising." (PMID 37623437, 2023). "In addition, in cervical cancer (CC) studies, the downregulation of Derlin1 affects the activation of the AKT/mTOR signaling pathway, and the absence of Derlin1 can inhibit the expression of p-AKT and p-mTOR." (PMID 35291564, 2022). "Here, we investigated that MAC induced apoptotic cell death of cervical cancer cells without regulating the cell cycle and promoted autophagy by inhibiting the phosphorylation of serine-threonine kinase B (Akt), mammalian target of rapamycin (mTOR), and 70-kDa ribosomal protein S6 kinase (p70S6K)." (PMID 36499465, 2022). "Thus, for a detailed mechanistic study, we first chose to clarify whether various signaling pathways, mTOR, ROCK, PI3K/AKT, and c-Src, which have been found to be related to cervical cancer tumorigenesis or progression, were involved." (PMID 35597782, 2022). "Although in this work we could not directly examine its mechanistic role in cervical cancer development, we compared the activities of the PI3K/AKT/mTOR pathway, apoptosis, and EMT markers between cancerous and paracancerous tissues of cervical cancer patients." (PMID 34589516, 2021). "Besides, more patients had actionable variants of level 3 than level 4 (39.53% vs 4.65%), as nearly a quarter of the cervical cancer patients had actionable of alterations in PIK3CA, which may confer sensitivity to the PI3K or mTOR inhibitors." (PMID 35071000, 2021). "The PI3K/Akt signaling pathway and the mammalian target of rapamycin (mTOR) signaling pathways are two pathways crucial to many aspects of cell growth and survival in cancers, and a recent study has revealed that INPP4B suppressed the PI3K/Akt/mTOR signaling in cervical cancer cells." (PMID 35070988, 2021). "We hypothesized that cervix cancer patients with aberrations in this pathway would achieve clinical benefit (defined as objective response and prolonged stable disease) when treated with PI3K/AKT/mTOR pathway targeted agents." (PMID 25426553, 2014).
cervical carcinoma (continued). "Importantly, these alterations have therapeutic relevance: several PI3K/AKT/mTOR inhibitors have been investigated in early phase trials for gynecologic tumors, and the PI3Kα inhibitor alpelisib has shown preclinical efficacy against PIK3CA-mutant cervical carcinoma models." (PMID 41597409, 2026). "As any therapeutic approach, including mTOR inhibitors in recurrent cervical cancer, would consider patients with recurrent disease for whom no standard therapy is available anymore, respective tissue samples may not perfectly depict the molecular and clinical behavior of very advanced cancers." (PMID 37623437, 2023). "Because the current data focused on the most enriched pathway related to the TIME of TB in cervical cancer, specific details, such as gene-level biomarkers or specific aspects of molecular reaction in the PI3K/Akt/mTOR pathway, have not been elucidated." (PMID 36354662, 2022). "We examined the tumor expression of mTOR, HIF-1α, c-Myc, and PKM2 in pre-chemotherapy cervical cancer tissues between chemotherapy responders and non-responders by immunohistochemistry." (PMID 27492148, 2016). "Our previous study have proved that Zey could simultaneously inhibit PI3K/AKT/mTOR and MAPK/ERK pathways (Data not published), indicating its potent activity against cervical carcinoma." (PMID 28490807, 2017).
osteosarcoma (330 papers, 2008 to 2026). A usually aggressive malignant bone-forming mesenchymal neoplasm, predominantly affecting adolescents and young adults. "Recent studies have demonstrated that the PI3K/AKT/mTOR pathway is implicated in autophagy arrest in osteosarcoma cells." (PMID 38434350, 2024). "Knocking down ANGPTL4 in osteosarcoma cells causes an accumulation of branch chain amino acids, by activating the mTOR signaling pathway and promoting the development of osteosarcoma." (PMID 38586328, 2024). "mTOR-associated signaling networks have been implicated in the development of various cancer types, including osteosarcoma." (PMID 36681687, 2023). "Because of its close linkage with Osteosarcoma, mTOR pathways, and the associated genes can serve as a therapeutic target for the disease." (PMID 37081847, 2023). "This consideration, together with our finding that magnesium deprivation causes mTOR hypophosphorylation at S2448, suggests that the antiproliferative effect of magnesium deficiency in osteosarcoma cells is mediated by mTOR." (PMID 33923895, 2021). "The overexpression of mTOR in osteosarcoma is associated with higher risk of progression and poorer survival." (PMID 34069999, 2021). "ERβ-induced autophagy in osteosarcoma was associated with downregulating the expression of P62 and p-mTOR." (PMID 32054506, 2020). "ERβ-induced autophagy in osteosarcoma was associated with downregulating the P62 expression level and inhibiting mTOR activation." (PMID 32054506, 2020). "Akt-mTOR and Akt-Bad are important intracellular signaling pathways, and are known to be closely associated with the progression of tumors, including osteosarcoma." (PMID 29510727, 2018). "In a separate systematic analysis, whole-genome siRNA screening of primary osteosarcoma cell cultures derived from a genetically engineered murine model revealed enrichment in pathways associated with protein translation and mTOR signaling." (PMID 27441088, 2016). "Preclinical studies demonstrated that sirolimus, the main mTOR inhibitor, blocks the ezrin pathway implicated in the metastatic migration of osteosarcomas." (PMID 26541413, 2015). "Growing evidence has revealed that PI3K/AKT/mTOR signaling pathway takes part in oncogene activating mutations, oncogene proliferation, and inactivation of cancer suppressor genes in various cancers including osteosarcoma." (PMID 29750154, 2018). "The PI3K/mTOR pathway has been implicated in osteosarcoma cell survival and proliferation in vivo." (PMID 26807203, 2015). "Additionally, increased STAT3 cytosolic level may suggest the inhibition of mTOR signaling as the crosstalk between these pathways has been implicated in several malignant diseases, e.g., osteosarcoma." (PMID 35163154, 2022). "Mechanistically, TRIM17 regulates FTO degradation via ubiquitination, modulates PDK1 gene methylation, and thereby activates the AKT/mTOR signaling pathway, promoting osteosarcoma malignancy." (PMID 41145484, 2025). "Aberrant activation of the PI3K/AKT/mTOR signaling pathway is a central driver of malignant progression in osteosarcoma (OS)." (PMID 40979744, 2025). "PDGFRB encodes a cell-surface tyrosine kinase receptor that, in osteosarcoma HOS cells, drives aerobic glycolysis through the PI3K/AKT/mTOR/c-Myc pathway while preserving ΔΨm." (PMID 41040657, 2025). "Since Rapamycin, an mTOR inhibitor, has already been evaluated for its safety and pharmacokinetics in canine osteosarcoma, it can be used in comparative STS studies." (PMID 41375061, 2025). "Studies have shown that the aberrant activation of the PI3K/Akt/mTOR pathway is a pivotal event in osteosarcoma development." (PMID 40283955, 2025).